NUAK2 (NUAK family kinase 2)
Description:
Stress-activated kinase involved in tolerance to glucose starvation. Induces cell-cell detachment by increasing F-actin conversion to G-actin. Expression is induced by CD95 or TNF, via NF-kappa-B. Protects cells from CD95-mediated apoptosis and is required for the increased motility and invasiveness of CD95-activated tumor cells. Phosphorylates LATS1 and LATS2. Plays a key role in neural tube closure during embryonic development through LATS2 phosphorylation and regulation of the nuclear localization of YAP1 a critical downstream regulatory target in the Hippo signaling pathway.
Synonyms: SNARK; FLJ90349; ANPH2
Tractability: Small molecule: a high-quality ligand is known; it belongs to a druggable protein family. PROTAC: ubiquitination databases record sites on it; a small molecule that binds it is known.
Target class: Enzyme; Protein Kinase; Kinase; CAMK protein kinase group; CAMK protein kinase NuaK subfamily; CAMK protein kinase CAMK1 family
Chemical probes: HTH-02-006 (high quality), WZ4003 (high quality)
Gene: Protein-coding gene on chromosome 1 (205,302,063 to 205,321,745, reverse strand). Ensembl gene ENSG00000163545.
Subcellular location (Human Protein Atlas): Cytosol; Nucleoplasm
Gene Ontology:
Molecular function: ATP binding; magnesium ion binding; protein binding; protein serine kinase activity; protein serine/threonine kinase activity; protein kinase activity
Biological process: actin cytoskeleton organization; cellular response to glucose starvation; negative regulation of apoptotic process; protein localization to nucleus; protein phosphorylation; regulation of hippo signaling
Genetic constraint (gnomAD): Loss-of-function variants: 17 observed, 26.5 expected, observed/expected ratio (o/e) 0.64, 90% interval 0.44 to 0.96. The upper end of that interval is the gene's LOEUF score, 0.96, which puts it in group 4 of 6, group 1 being the genes least tolerant of losing a copy. Missense variants: 652 observed, 771.89 expected, observed/expected ratio (o/e) 0.84, 90% interval 0.79 to 0.9. Synonymous variants: 295 observed, 320.46 expected, observed/expected ratio (o/e) 0.92, 90% interval 0.84 to 1.01.
Homologues: Orthologues: chimpanzee NUAK2 (99% identical), macaque NUAK2 (97% identical), pig NUAK2 (89% identical), dog NUAK2 (87% identical), guinea pig NUAK2 (87% identical), mouse Nuak2 (87% identical), rabbit NUAK2 (86% identical), rat Nuak2 (86% identical), zebrafish nuak2 (55% identical), tropical clawed frog nuak2 (53% identical), Drosophila melanogaster Nuak (40% identical), Drosophila melanogaster Snrk (22% identical), and 4 more. Paralogues in human: NUAK1 (58% identical), SIK3 (28% identical), SIK2 (28% identical), SIK1 (28% identical), BRSK1 (26% identical), BRSK2 (26% identical), PRKAA2 (25% identical), PRKAA1 (25% identical), MELK (24% identical), SNRK (24% identical), HUNK (23% identical), TSSK1B (21% identical), and 5 more.
Diseases named in the same sentence as NUAK2 in open-access papers:
NUAK2 is named in the same sentence as 60 diseases in open-access papers, as found by Europe PMC text mining. Sharing a sentence is not in itself a finding about the gene and the disease. The quoted sentences say what the papers report.
breast carcinoma (15 papers, 2011 to 2025). "For example, NUAK1 and NUAK2 downregulation has been linked to reduced motility and invasiveness of renal and breast cancer cell lines, whereas overexpression of NUAK2 in HepG2 human hepatocytes increases survival following glucose starvation." (PMID 34685740, 2021). "Pharmacological inhibition or loss of NUAK2 reduces the growth of cultured cancer cells and mammary tumors in mice." (PMID 30158528, 2018). "Based on our microarray and in silico analyses,NUAK2 is regulated during the murine estrous cycle,dysregulated in ovarian cancer and putatively contains a driver mutation in ovarianand breast cancer." (PMID 21423607, 2011). "Together, these observations predict that claudin-low breast cancers will generally exhibit higher NUAK2 expression and enhanced vulnerability to GPX4 inhibition." (PMID 35523770, 2022). "We find that NUAK2 is amplified in a subset of breast cancers and is most highly expressed in the claudin-low subtype." (PMID 35523770, 2022). "Next, we analyzed the METABRIC breast cancer data set of 2,173 patient samples in cBioPortal and found that ~25% had amplification of NUAK2." (PMID 35523770, 2022). "Breast cancer subtype analysis of the METABRIC data revealed that NUAK2 mRNA expression was highest in the claudin-low subtype." (PMID 35523770, 2022). "Initial reports regarding NUAK1 and NUAK2 function indicate a potential role in apoptosis resistance as assessed in MCF7 human breast cancer cells following starvation." (PMID 34685740, 2021). "Stratification into breast cancer subtypes show a more complicated relationship; NUAK2, for example, is correlated with improved survival in ER- but is worse in ER+ breast cancer." (PMID 34084284, 2021). "CD95-induced apoptosis is severely impeded when NUAK1 and NUAK2 proteins were silenced in MCF7 breast cancer, human cervix carcinoma (HeLa), and colorectal cancer cell lines." (PMID 34685740, 2021). "In Luminal A breast cancer, higher expression of MARK2, NUAK2, and PAK1 was significantly associated with improved survival in both pre- and post-chemotherapy groups." (PMID 34084284, 2021). "Tumor necrosis factor α and CD95 induce NUAK2 expression in breast cancer cells to promote invasiveness and survival." (PMID 30622137, 2019). "Using a small interfering RNA (siRNA) kinome screen to monitor YAP/TAZ localization in breast cancer cells, we identified NUAK2, an AMPK family member, as a positive regulator of YAP/TAZ activity that directly inhibits LATS-mediated phosphorylation of YAP/TAZ." (PMID 30158528, 2018). "Our findings are in line with previous studies reporting increases in cell death by NUAK1 silencing in colorectal cancer cells, reduced survival of breast cancer cells by silencing of NUAK2, and reduced proliferation of cervical cancer cells by silencing of NUAK2." (PMID 37188272, 2023). "NUAK2 alterations were most prevalent in breast cancers compared to other cancer types." (PMID 35523770, 2022). "NUAK2 is amplified along with MDM4 in a subset of breast cancers, particularly the claudin-low subset, suggesting that this may predict vulnerability to GPX4 inhibitors." (PMID 35523770, 2022). "TGF-β transcriptionally induced both NUAK1 and NUAK2 in various mammalian cell types, including mouse breast epithelial cells, human breast cancer cells and human immortalized keratinocytes, as well as primary human foreskin fibroblasts, in a TβRI- and SMAD4-dependent manner." (PMID 34282782, 2021). "NUAK2 expression also increased the motility and invasive character of breast cancer cells." (PMID 34282782, 2021). "Our preliminary analysis of breast cancer patient samples did not reveal an association between NUAK2 expression and grade; however, a more thorough analysis of subtypes in breast or other cancers may uncover such links." (PMID 30158528, 2018).
breast carcinoma (continued). "Consistent results were independently found in MDA-MB231 breast cancer cells, wherein YAP, TAZ and TEAD were again shown to bind to NUAK2 enhancer sequences and to positively regulate NUAK2 mRNA expression." (PMID 38939918, 2024). "The co-amplification of NUAK2 and MDM4 in breast cancer suggests a potential therapeutic application." (PMID 35523770, 2022). "In all breast cancer combined, high expression of LKB1, AMPK, LYK5, MARK1, MARK2, NUAK2, PAK1 (both probe sets), SIK1, SIK2, BRSK1, BRSK2, SNRK, and QSK was positively correlated with improved survival compared to low expression of these genes." (PMID 34084284, 2021). "In SMAD4-null human breast carcinoma MDA-MB-468 cells, NUAK2 protein expression and weak inducibility by TGFβ were rescued upon reconstitution of SMAD4 in the cells." (PMID 30622137, 2019). "NUAK2 acts as a potent YAP/TAZ activator, inhibiting LATS1/2 kinase activity, leading to nuclear accumulation of YAP and ultimately tumorigenesis in liver and breast cancers." (PMID 40770117, 2025). "The close proximity of NUAK2, which we find is commonly co-amplified with MDM4 in breast cancer, may fortuitously confer a vulnerability to GPX4 inhibition that could be exploited for therapy." (PMID 35523770, 2022). "Our identification of NUAK2 but not NUAK1 in the TNBC lines, an observation we confirmed in separate studies, suggests that NUAK2, rather than NUAK1, may play a more prominent role in promoting YAP/TAZ activity in breast cancer." (PMID 40869130, 2025).
liver cancer (9 papers, 2018 to 2025). An epithelial or non-epithelial malignant neoplasm that arises from the liver. "Studies performed in mouse models (e.g., YAP-inducible overexpression mouse models that cause hepatomegaly and eventually liver tumorigenesis) of liver cancer indicate that NUAK2 knockdown decreases cell proliferation in YAP-dependent liver tumors and HuCCT cells." (PMID 34685740, 2021). "Recent studies have already shown that silencing of NUAK2 blocks proliferation and promotes apoptosis of human melanoma cells and liver cancer cells." (PMID 39071701, 2024). "This highlights the significance of NUAK2 as a potential therapeutic target for controlling YAP-driven tumor growth in liver cancer." (PMID 37627077, 2023). "In the context of liver cancer, NUAK2 was identified as a mediator for YAP-induced hepatomegaly and carcinogenesis." (PMID 37627077, 2023). "In liver cancer, targeting and inhibiting NUAK2 activity results in the decreased growth of YAP-dependent tumors." (PMID 37627077, 2023). "NUAK2 has been shown to be a target of YAP in liver cancer and is actively required for YAP driver growth (PMID: 30446657)." (PMID 34354115, 2021). "Here, using liver cancer as a model, we identify NUAK2 as an essential mediator of YAP-driven hepatomegaly and tumorigenesis in vivo." (PMID 30446657, 2018). "Considering the strong functional relationship between YAP and NUAK2, we assessed whether liver cancer cell lines would show a selective response towards NUAK2 inhibition depending upon YAP/TAZ activity." (PMID 30446657, 2018). "NUAK family kinase 2 (NUAK2) activates YAP by enhancing actin polymerization and myosin activity, fostering liver cancer cell proliferation." (PMID 40066231, 2025). "Inhibition of NUAK2 suppresses YAP-driven hepatomegaly and liver cancer growth, offering a new target for cancer therapy." (PMID 30446657, 2018). "In liver cancer HuCCT-1 cell line, YAP binds to the NUAK2 promoter upregulating its expression." (PMID 34685740, 2021). "In addition to the short-term effects of Nuak2 knockout in YAP-mediated overgrowth, we assessed the role of NUAK2 in a longer-term model of YAP-activation that leads to liver cancer." (PMID 30446657, 2018).
melanoma (9 papers, 2011 to 2024). A malignant, usually aggressive tumor composed of atypical, neoplastic melanocytes. "NUAK2 has been mostly implicated in human cancer development by amplifications in human melanoma, although copy number gains of 1q32 are found in other epithelial malignancies." (PMID 30446657, 2018). "Additionally, NUAK2 silencing has been associated with mTOR downregulation in cellular models of melanoma." (PMID 34685740, 2021). "In melanomas and skin tumors, NUAK2 expression positively correlated with the Akt Ser-473 phosphorylation." (PMID 38135881, 2023). "NUAK2 participates in the regulation of proliferation and migration of melanoma cells by regulating the cell cycle." (PMID 36125617, 2022). "NUAK2 is frequently amplified in a range of human cancers, forming part of the 1q32 amplicon common in melanoma, glioblastoma and other cancers." (PMID 30446657, 2018). "In acral melanomas there is a relationship between PTEN loss and amplification of the AMPK-related kinase NUAK2; importantly, in these melanomas, the presence of both PTEN loss and NUAK2 amplification was associated with poor prognosis." (PMID 29156643, 2017). "Reports on the role of NUAK2 in tumours of different origin vary: in melanoma, NUAK2 (SNARK) levels correlate negatively with patient survival, whereas in ovarian cancer patients, an opposite trend was reported." (PMID 26196184, 2015). "We recently identified NUAK2 at 1q32 as a promising oncogene in acral melanomas and reported its significant roles in tumorigenesis in melanoma cells using both in vitro and in vivo analyses." (PMID 21911917, 2011). "In this review, we discuss the oncogenic role of NUAK2 and its clinical significance in melanoma patients, as well as its regulation by intracellular signaling pathways including LKB1 and CaMKKβ in melanoma cells." (PMID 21911917, 2011). "NUAK2, a gene at this locus, has regulatory impacts on the proliferation and migration of melanoma cells." (PMID 21911917, 2011). "Here we review genomic aberrations of melanomas focusing on acral melanomas to emphasize the possible roles of NUAK2 in tumorigenesis in general and suggest that NUAK2 has pivotal roles in acral melanomagenesis." (PMID 21911917, 2011). "Public databases showed that NUAK2 is highly expressed in a range of human cancers such as melanoma, glioblastoma, or other cancers; thus, suggesting that it might be associated with tumor progression and cancer development." (PMID 39071701, 2024). "Moreover, in human melanoma, knockdown of NUAK2 decreases the migration and induces cellular senescence of melanoma cells by regulating the expression of N-cadherin, a cell transmembrane protein, and function to mediate YAP-dependent cell−cell adhesion." (PMID 39071701, 2024). "Likewise, NUAK2 silencing in different melanoma cell lines reduces the migration and invasion of these cells." (PMID 34685740, 2021). "Indeed, analysis of the cancer genome atlas (TCGA) database revealed NUAK1 and NUAK2 deregulation in lung, breast, liver, ovarian, and melanoma tumors." (PMID 34685740, 2021). "The knockdown of NUAK2 using siRNA or shRNA reduces cell proliferation in vitro and tumor growth in vivo in melanomas, and the extent of those reductions of cell proliferation varies depending on the different genomic aberrations of melanoma cells." (PMID 21911917, 2011). "However, TCGA database analysis exhibits alterations in NUAK2 expression, comprising mostly amplifications in reproductive organ tumors, such as breast, ovarian, and uterine, in addition to other tumor types, including melanoma, liver, and lung cancers." (PMID 34685740, 2021). "However, NUAK2 functions during apoptosis are different depending on the melanoma cell lines." (PMID 21911917, 2011).
melanoma (continued). "First, high level and activity of AhR mediates the invasive/dedifferentiated phenotype of melanoma through the direct regulation of the expression of many genes involved in invasion (COL1A1, COL6A1, COL6A2, CYR61, STC2...) and dedifferentiation phenotypes (CCL2, NTM, NUAK2, SOX9, ABCG2...)." (PMID 36305167, 2022). "Interestingly, those impacts of NUAK2 on melanoma patient survival are significant at relapse-free survival of acral melanomas compared to weak significances at Non-CSD melanomas and overall survival." (PMID 21911917, 2011).
anencephaly (5 papers, 2021 to 2025). A rare neural tube defect during pregnancy, resulting in the absence of a large portion of the brain and skull in the fetus. "Specifically, germline homozygous pathogenic variants in NUAK2 were identified in three fetuses with anencephaly, thus implicating this gene as a critical regulator of neural tube closure." (PMID 41008661, 2025). "Previous studies have shown that adipocyte‐specific ablation of Nuak2 promotes adipose inflammation, and that NUAK2 mutation in humans causes anencephaly." (PMID 35343079, 2022). "A case report of a family with three consecutive fetuses born with anencephaly identified a recessive deletion in the NUAK2 gene, indicating a possible genetic cause." (PMID 34685740, 2021). "NUAK2 deletion has been associated with anencephaly in humans." (PMID 34685740, 2021). "In a family with repetitive cases of anencephaly, exome sequencing of two fetuses with anencephaly and their parents identified a recessive germline mutation (22 base pair deletion and 1 base pair insertion) in the NUAK2 gene." (PMID 34282782, 2021). "Notably, the current identified c.487G>A missense variant occurs in the same protein kinase domain (c.412_433delinsG) as the previously reported homozygous variant in NUAK2 associated with anencephaly (MIM #619452; ANPH2)." (PMID 41008661, 2025). "The association between biallelic causative variants in the TRIM36 (MIM*609317, TRIPARTITE MOTIF-CONTAINING PROTEIN 36) and in the NUAK2 (MIM*608131, NUAK FAMILY, SNF1-LIKE KINASE, 2) genes with anencephaly remains provisional, as it has been described in one family each." (PMID 41008661, 2025).
hepatocellular carcinoma (5 papers, 2016 to 2025). A malignant tumor that arises from hepatocytes. "In hepatocellular carcinoma, NUAK2 silencing or pharmacological inhibition impaired proliferation through modulation of YAP signaling, and YAP-driven NUAK2 was shown to reinforce YAP activity via actomyosin cytoskeleton remodeling." (PMID 40770117, 2025). "TGF-β signaling is an important pro-fibrogenic factor in the liver and NUAK2 silencing in Huh7.5.1 hepatocellular carcinoma cells reduce TGF-β signaling." (PMID 34685740, 2021). "Consequently, NUAK2 facilitates HCV replicative potential and allows pro-fibrogenic TGF-β signaling, which accelerates hepatic fibrosis progression and eventually causes hepatocellular carcinoma." (PMID 34685740, 2021). "To extend our findings of YAP-mediated NUAK2 induction to human cancer, we analyzed the expression profiles of YAP and NUAK2 and the correlation of YAP and NUAK2 in hepatocellular carcinoma (HCC) through bioinformatics analyses." (PMID 30446657, 2018).
cervical carcinoma (4 papers, 2019 to 2025). A carcinoma arising from either the exocervical squamous epithelium or the endocervical glandular epithelium. "For example, in cervical cancer, NUAK2 knockdown reduced cell proliferation, migration, and expression of EMT markers via interaction with CYFIP2." (PMID 40770117, 2025). "Protein analysis confirmed that NUAK1 and NUAK2 were induced in a time-dependent manner in human fibroblasts, mammary cells (data shown for NUAK2 only), and HaCaT and human cervical carcinoma HeLa cells." (PMID 30622137, 2019). "In melanomas, NUAK2 affects cell cycle progression and migration, whereas it affects gene expression in human cervical cancer cells under stress." (PMID 30622137, 2019). "Fox example, NUAK family kinase 2 (NUAK2) may regulate CYFIP2 expression to promote cervical cancer cell proliferation, migration, invasion and epithelial-to-mesenchymal transition." (PMID 37735711, 2023).
colorectal cancer (4 papers, 2011 to 2023). A primary or metastatic malignant neoplasm that affects the colon or rectum. "However, other data suggest that NUAK2 might have tumor suppressive roles in the context of a colorectal cancer model." (PMID 30446657, 2018). "Inhibition of NUAK2 with WZ4003 blocked nuclear accumulation of YAP/TAZ in SW480, an APC mutant colorectal cancer cell line, as well as in TCCSUP, T24, and RT112, three bladder cancer-derived lines." (PMID 30158528, 2018).